TNF (tumor necrosis factor)
Diseases named in the same sentence as TNF in open-access papers (continued):
Sharing a sentence is not in itself a finding about the gene and the disease.
malaria (continued). "Malaria may also cause iron deficiency through increasing inflammatory cytokines such as tumor necrosis factor-α (TNF-α)." (PMID 30275421, 2018). "In addition, cytokines such as IL-12 and TNF are also crucial for controlling Plasmodium infection and decrease the risk of fever, clinical malaria, and parasitemia." (PMID 30116753, 2018). "Ex vivo, Vγ9Vδ2 T-cell proliferation, TNFα, and IFNγ production and immune-modulatory gene expression was also negatively associated with prior malaria episodes—indicating decreased peripheral blood Vγ9Vδ2 T-cell activity with increasing exposure to the parasite." (PMID 30538708, 2018). "Monocytes from PBMCs of Papua New Guinean children with severe malaria responded in vitro to P. falciparum iRBCs by secreting higher quantities of TNF-α, MIP-1β, and MIP-1α (implicated in monocyte activation and recruitment) than healthy children or children with uncomplicated malaria." (PMID 30581439, 2018). "Years of studies on malaria have shown a critical role for proinflammatory cytokines in pathogenesis of the disease and high levels of proinflammatory cytokines such as TNFα, IL-6 and IFNγ have long been linked to acute phases of malaria, including cerebral malaria." (PMID 29495555, 2018). "High ratios of TNFα to IL-10 have also been linked to severe malaria in children from this region." (PMID 28337195, 2017). "We found that higher frequencies of Vδ2+ T cells, as well as higher percentages of Vδ2+ T cells that produced IFNγ and TNF upon malaria antigen stimulation, were both associated with a significantly lower odds of subsequent P. falciparum infection in the subsequent year." (PMID 28904345, 2017). "Driving the hypochromic morphology observed with both IC and CHQ-treated animals is a synchronous release of parasite pyrogens such as tumour necrosis factor-α (TNF-α) and interleukin-1β (IL-1β) that are also associated with anaemia, various pathologies and death from malaria." (PMID 27098750, 2016). "Our data suggest a graded activation of pathways downstream of the pro-inflammatory cytokines IFNγ, TNF, and IL-1β that is associated with prior malaria-exposure, with naïve individuals having the greatest activation and malaria-experienced asymptomatic individuals having the least." (PMID 27506615, 2016). "TNFα is increased in malaria patients and has been associated with the severity of infection." (PMID 27784899, 2016). "However, IFN-γ and TNF are among the major cytokines shown to be associated with immunity against malaria, hence the study provides valid insight on the effect of CTX prophylaxis on antigen-specific CD4+ T cells immune responses." (PMID 27165269, 2016). "However, despite these several evidences of polymorphism in TNF gene in relation to malaria susceptibility in the studies, a larger number of samples and different clinical and epidemiological scenarios are necessary to confirm the associations." (PMID 26858717, 2016). "Also, fever in malaria is thought to be caused partly by TNF and other pyrogenic cytokines released as part of the human immune response to products of schizont rupture." (PMID 26390866, 2015). "In an animal malaria model, a study showed an association between MCs and the elevation of serum TNF, which could contribute to malaria protection." (PMID 25879828, 2015). "Noteworthy, TNF polymorphisms are common and may play a role in TNF levels in the context of malaria." (PMID 26271921, 2015). "Thirdly, the relationship between TNF genotype and susceptibility to malaria may depend on population-specific factors." (PMID 26088606, 2015). "In this cohort study, bias may have occurred if there was differential loss to follow-up such that the risk of being lost to follow-up was related both to malaria and TNF genotype, or if there were group differentials in the detection of malarial episodes." (PMID 26088606, 2015).
malaria (continued). "We hypothesized that CD4+ T cells producing the pro-inflammatory cytokines IFNγ and/or TNFα are associated with protection from malaria, and that T cell production of the regulatory cytokine IL-10 may interfere with the acquisition of protection." (PMID 24415936, 2014). "Population differences in susceptibility or resistance to malaria according to TNF SNPs may be a result of diverse evolutionary pressure between ethnicity, as well as different parasite strains and incidence of severe forms of disease." (PMID 25124540, 2014). "However, many haplotypes appear to markedly increase TNF levels, indirectly contributing to malaria susceptibility." (PMID 25038626, 2014). "Taken together, transient elevation of TNF may be beneficial since it enhances parasite clearance while sustained release of TNF in severe malaria is associated with increased malaria morbidity and perhaps mortality." (PMID 24669217, 2014). "Importantly, the down regulation of TNF-α production and consequent resistance to severe malaria, has been linked to the ability to produce the immuno-regulatory cytokine, Transforming growth factor (TGF)-β." (PMID 24934404, 2014). "Interestingly, the opposite relationship was observed between total TNFα+ producing cells and the duration since last episode of malaria, with more recent malaria associated with a lower frequency of TNFα -producing cells (Spearman's Rho = 0.23, P = 0.041)." (PMID 24415936, 2014). "In univariate Cox proportional hazards analysis evaluating time to next episode of malaria, a higher frequency of CD4+ T cells producing any IFNγ or IL10, or the combinations IFNγ+/IL-10+/TNFα− and IFNγ−/IL-10+/TNFα− was associated with a significantly increased hazard of malaria (left columns)." (PMID 24415936, 2014). "Thus, although TNFα is unquestionably an important mediator of malaria immunity and pathogenesis, it remains possible that the observed genetic associations with TNFA polymorphisms arise from functional variation in neighbouring genes rather than TNF itself." (PMID 24312262, 2013). "In addition, the TNF-376 promoter SNP (rs1800750) was identified to have an association with clinical malaria." (PMID 22615793, 2012). "Finally, a critical role for mast cell–derived TNF in limiting parasitaemia in a murine model of malaria has been demonstrated by reconstituting mast cell–deficient mice with mast cells derived from wild-type and TNF-deficient mice." (PMID 22577358, 2012). "The IL1B gene -5839C > T and IL4R 1902A > G polymorphisms and IL12RB1 -1094A/-641C and TNF -1031 T/-863A/-857 T/-308 G/-238 G haplotypes were associated with malaria susceptibility after population structure correction (p = 0.04, p = 0.02, p = 0.01 and p = 0.01, respectively)." (PMID 23217179, 2012). "SNPs at position −1031,-857,-308,-238 and −863 in the promoter region of TNF gene exhibit differential associations to malaria and TNF production in different populations suggesting that individual TNF responses may be genetically determined." (PMID 22947458, 2012). "In the uncomplicated malaria group, homozygosity for the Δ22 insertion allele was associated with elevated IL-6 (p = 0.04), and at least one long GT repeat allele was associated with elevated serum TNF levels (p = 0.007)." (PMID 22336003, 2012). "In previous studies, TNF polymorphisms have been related to severe malaria." (PMID 22947458, 2012). "Population differences in susceptibility or resistance to malaria according to TNF SNPs may be a result of diverse evolutionary pressure between ethnicities, as well as different parasite strains and incidence of severe forms of disease." (PMID 23316245, 2012). "IL12RB1 and TNF haplotypes were associated with malaria susceptibility." (PMID 23217179, 2012). "In Sri Lanka, the TNF −308A allele was associated with severe malaria and other infections." (PMID 23316245, 2012).
malaria (continued). "After vaccination with RTS,S/AS01E, an increasing frequency of TNFα producing, CS-specific CD4+ cells detected using ICS was associated with a reduced risk of clinical malaria (HR = 0.64 for each 10 fold increase in the frequency of CD4+ TNFα+ T cells, 95%CI 0.49–0.86, p = 0.002)." (PMID 21998698, 2011). "The frequency of CD4+ TNFα+ T cells on ICS was associated with protection from clinical malaria." (PMID 21998698, 2011). "SNPs of the TNF promoter have been reported to be associated with susceptibility to severe malaria." (PMID 20846452, 2010). "The original proposal that malarial toxin operates through inducing generation of TNF and related cytokines was greatly strengthened when immunizing mice against GPI and then infecting them with one of the mouse malaria parasites protected against certain pathology that TNF causes on injection." (PMID 17029647, 2006). "Twenty-five years ago our group proposed that TNF might cause the bone marrow depression seen in malaria." (PMID 17029647, 2006). "However, the relationship between TNF-α -308G >A gene polymorphism (rs1800629) and the severity of Plasmodium falciparum (P. falciparum) malaria remains unclear, which prompts a meta-analysis to obtain more precise estimates." (PMID 37910577, 2023). "The IL-12 levels were reported to be lower in patients with severe malaria, particularly in those with severe malarial anemia, because the ingestion of malarial pigments by monocytes promoted the overproduction of IL-10, TNF-α, or TGF-β, and caused a lower production of IL-12." (PMID 35954703, 2022). "In another study with children living in a holo-endemic area of Western Kenya, higher ratios of plasma IL-10 to TNF levels were strongly associated with protection against severe malaria anemia, providing evidence that IL-10 may be protective by inhibiting TNF activity." (PMID 30809232, 2019). "It is described, in a recent review, that TNF polymorphisms could control parasite development in the early stages of infection, but they can enlarge the probability of patients to develop severe malaria syndromes." (PMID 31871954, 2019). "Indeed, in future studies it would be preferable to explore other immune responses induced by these PSNPs vaccines in the context of blood-stage malaria, including investigating other cytokines (i.e., TNF, IL-5, IL-17) in addition to the hallmark Th1 and Th2 cytokines IFN-γ and IL-4, respectively." (PMID 30930890, 2019). "Also, TNF-238 G allele (rs361525) shows opposing effects on vulnerability to cerebral malaria and severe malaria anemia suggesting differential roles of TNF in the spectrum of severe malaria syndromes." (PMID 31417551, 2019). "However, it is well-established that enhanced levels of TNF-α are associated with a greater risk of the development of severe malaria in humans and mice deficient for this cytokine were resistant to the development of cerebral malaria (CM) following Plasmodium berghei infection." (PMID 31867283, 2019). "Recent reports have shown that heme, a known malaria danger-associated molecular pattern released during parasite egress, robustly induces NETs but not infected red blood cells, merozoites, and digestive vacuoles containing HZ, in tumor necrosis factor (TNF)-α-primed human neutrophils." (PMID 31905972, 2019). "We hypothesize that malaria may be causally linked to iron deficiency in African children by increasing concentrations of the iron hormone hepcidin, as well as increasing inflammatory cytokines, such as tumor necrosis factor-α (TNF-α)." (PMID 30275421, 2018). "Interestingly, TNF is located within chromosome 6p21.3 linked to parasitemia and mild malaria in humans, and the corresponding chromosomal region in mice is genetically linked to mild malaria and cerebral malaria." (PMID 30533319, 2018).
malaria (continued). "Moreover, the results suggest that combinations of genotypes (including IL6-176G > C) are associated with a decreased or increased risk of developing clinical manifestations of malaria and may also influence plasma TNF and IL-6 levels." (PMID 25038626, 2014). "However, the functional role of TNF-promoter polymorphisms that are associated with severe malaria still remains open to question especially as the surrounding MHC class III region has many other interesting immunological genes and complex patterns of linkage disequilibrium." (PMID 24312262, 2013). "Finally, we analysed the influence of cord blood TNF-α and IL-1β levels on severe malaria risk." (PMID 24130857, 2013). "Furthermore, in malaria, alleles associated with sickle-cell anemia, thalassemias, and glucose-6-phosphate dehydrogenase deficiency confer protective effects, whereas polymorphisms in the TNF-α gene have been linked to increased risk of cerebral malaria (CM)." (PMID 22096530, 2011). "In this study, the association between malaria disease pathogenicity/severity and (GT)n repeat polymorphism in the promoter region of the inducible HO-1 including the effect of cadmium exposure (potent inducer of HO-1 transcription) as well as polymorphism of TNF were investigated." (PMID 20846452, 2010). "SNPs at positions -1031, -857, -376 (rs1800750, G>A), -308 and -238 in the proximal enhancer of the TNF gene exhibit differential associations to malaria and TNF production in different populations suggesting that individual TNF responses may be genetically determined." (PMID 18194515, 2008). "The highest concentrations of adipsin, C5a, TNF‐α and IL‐6 were observed in women with preeclampsia coexisting with malaria." (PMID 41536443, 2026). "Plasma adipsin showed strong positive correlations with C5a (ρ = 0.695), IL‐6 (ρ = 0.687), and TNF‐α (ρ = 0.645), and moderate correlations with malaria parasite density (ρ = 0.553), IL‐8 (ρ = 0.475) and C3a (ρ = 0.437) (p < 0.001 for all)." (PMID 41536443, 2026). "In this study, APOA1 gene polymorphisms, serum levels of APOA1, and inflammatory markers (TNF-α and IL-6) were investigated in Nigerian children with uncomplicated malaria." (PMID 40061813, 2025). "While our experiments examine malaria parasite infection using the rodent malaria model, P. berghei, it remains to be explored if TNF pathway components similarly influence infection outcomes with the human malaria parasite, P. falciparum." (PMID 40608824, 2025). "Functional enrichment analysis revealed that modules with a strong correlation with uveitis, including the TNF, malaria, and IL-17 signaling pathways, were consistent with the findings of our previous study." (PMID 40718791, 2025). "Previous studies have shown that certain components of FFR can downregulate pro-inflammatory cytokines such as TNF-α and IL-1β, which are involved in the pathogenesis of neuroinflammation during malaria." (PMID 40892845, 2025). "This indicates that TNF-α levels rise in conjunction with parasite counts, reflecting the pro-inflammatory role of TNF-α in malaria pathogenesis." (PMID 40061813, 2025). "Children with malaria exhibited higher levels of IL-6 and TNF-α compared to controls, consistent with the inflammatory response characteristic of malaria infection." (PMID 40061813, 2025). "gambiae, demonstrating the effects of TNF signaling in limiting malaria parasite survival and immune cell regulation." (PMID 40608824, 2025). "It is known that malaria disease induces multiple inflammatory signs besides several cytokines like TNF-α and IL-6 playing a significant role in the inflammatory process." (PMID 40917784, 2025). "The same study emphasized the importance of TNF and MV production in determining the severity of malaria." (PMID 39868784, 2025). "In this study, we establish integral roles of mosquito TNF signaling in mediating anti-Plasmodium immune responses that limit malaria parasite survival in the mosquito host." (PMID 40608824, 2025).
malaria (continued). "While not observed in this mouse model, additional cytokines including IFN-γ, TNF-α, and IL-10 have been reported in the placenta of malaria-infected pregnant women." (PMID 40470930, 2025). "On the other hand, the immunohistochemistry investigation of TNF-α and IL-6 expressed strong positive reactions with pulmonary components that reflected the severity of malaria damage and lung inflammation of P. chabaudi." (PMID 40917784, 2025). "High levels of TNF-α and IL-6 in severe malaria cases corroborate previous findings on their role in the malaria pathogenesis." (PMID 40061813, 2025). "TNF-α exhibited the strongest positive correlation with parasite counts, emphasizing its pivotal role in malaria pathogenesis." (PMID 40061813, 2025). "TNF-α mediates inflammation, fever, and endothelial activation, contributing to malaria complications such as cerebral malaria and severe anemia." (PMID 40061813, 2025). "While cytokines such as IL-6 and tumor necrosis factor-α (TNF-α) have been extensively studied in malaria pathogenesis, the role of IL-2 remains poorly understood and inconsistently reported across studies." (PMID 41194029, 2025). "In malaria-endemic regions, children under five years of age are likely to experience dyserythropoiesis driven chiefly by inflammatory cytokines such as IL-6, TNF-α and IFN-γ." (PMID 40980010, 2025). "TNF, in particular, has been shown to mediate pathological effects during severe malaria by increasing vascular permeability, activating endothelial cells, and promoting leukocyte adhesion." (PMID 40014608, 2025). "Increased levels of IL-1β and TNF, beyond TGF-b and IL-10, are associated with the major severity of malaria." (PMID 38774541, 2024). "On the contrary, TNF‐α/IL‐10 and IL‐6/IL‐10 ratios were reduced when malaria‐infected children were compared with uninfected group in Malawi." (PMID 39240033, 2024). "Malaria‐infected children had relatively higher TNF‐α (p < .001), IFN‐ɣ (p < .001), IL‐1β (p < .001), IL‐6 (p < .001), GM‐CSF (p < .001), and IL‐10 (p < .001) levels than uninfected participants." (PMID 39240033, 2024). "The intense sequestration exacerbates the inflammatory response and cause cytokine storm, especially increasing IL‐10, GM‐CSF, IL‐6, IL‐1β, IFN‐ɣ, and TNF‐α levels, which promotes the progression of severe malaria." (PMID 39240033, 2024). "In our current investigation, we assessed the levels of IL-1β and TNF-α, two key players in the pathophysiologic aspects of cancer and malaria, particularly inflammation and pain." (PMID 38774541, 2024). "Upon stimulation with P. falciparum–infected erythrocytes, CD4+, γδ, and EMRA CD8+ T cells produced IFN-γ and/or TNF, indicating their ability to mediate responses that eliminate malaria parasites." (PMID 38716733, 2024). "In the context of malaria vaccines targeting clinical symptoms, those directed against TNF-α (tumor necrosis factor-alpha) show promise in reducing malaria-related symptoms such as fever." (PMID 39085983, 2024). "Targeting H3K4 methylation with WDR5 antagonists can be useful in controlling excessive inflammatory TNF and IL-6 production and thereby managing the pathogenesis of severe malaria." (PMID 38316918, 2024). "Malaria presents with enhanced release of TNF‐α, IFN‐ɣ, IL‐1β, IL‐6, GM‐CSF, and IL‐10, but downregulates IL‐3 and TGF‐β in Ghanaian children." (PMID 39240033, 2024). "In preclinical studies, anti-TNF-α therapies showed promise in mitigating severe malaria symptoms and reducing mortality." (PMID 38694310, 2024). "Since it has been shown that blood levels of cytokines are altered during malaria, levels of the serum cytokines TNF-α, IFN-γ, IL-10, and IL-6 of uninfected and PbA-infected mice at day 7 post-infection were determined using CBA analysis." (PMID 38787228, 2024).